BECN1 (beclin 1)
Diseases named in the same sentence as BECN1 in open-access papers (continued):
Sharing a sentence is not in itself a finding about the gene and the disease.
colorectal cancer (continued). "In this study, we assessed the patterns of Beclin 1 expression in a series of colorectal carcinomas with scope to investigate the clinicopathological role of this protein in the early steps of autophagosome formation." (PMID 20842118, 2010). "Interestingly, a recent report showed that BECLIN-1 knockdown results in OCCLUDIN levels increasing on membranes in colorectal cancer cells (and decreasing when autophagy is induced using Tat-Beclin1 peptide)." (PMID 40395982, 2025). "Therefore, the HMGB1/BECN1 axis, which is critical for colorectal cancer progression, can represent a therapeutic marker for patients with CRC, particularly those with radioresistance." (PMID 41164196, 2025). "IL-6 has been implicated as mediator of tumor progression and chemoresistance in multiple cancers such as NSCLC and colorectal cancer wherein IL-6 has been observed to modulate autophagy by inducing phosphorylation of BECN1 via the IL-6/JAK2/BECN1 signaling pathway." (PMID 40176914, 2025). "BRAF increases the levels of autophagic markers, such as LC3 and BECN1, in colorectal cancer cells." (PMID 38474411, 2024). "For example, Beclin1/autophagy signaling mediates Sox2-promoted chemoresistance, proliferation, stemness, migration, and invasion in colorectal cancer cells, and IL-6 activates autophagy via the IL-6/JAK2/BECN1 pathway, promoting chemotherapy resistance in colorectal cancer." (PMID 37303041, 2023). "Beclin 1 has an important role in the growth and metastasis of human colorectal cancer." (PMID 36230664, 2022). "VPS53 overexpression induces the autophagy signaling pathway, as exemplified by the increased expression of autophagy-related proteins, including LC3BII and Beclin 1, thus promoting autophagy and apoptosis and, in turn, impairing the proliferation, migration and invasion of colorectal cancer cells." (PMID 35805075, 2022). "The role of BECN1 in colorectal cancer development remains controversial." (PMID 36230664, 2022). "Additionally, the concentration of important proteins (sICAM-1, mTOR, Beclin-1, cathepsin B) involved in the pathogenesis and poor prognosis of colorectal cancer was also evaluated by ELISA." (PMID 33918514, 2021). "Initially, a colorectal cancer tissue micro array, containing mucosa (n = 10), adenoma (n = 18) and adenocarcinoma (n = 49) spots, was stained for expression of essential autophagy proteins LC3b, Atg7, p62 and Beclin-1." (PMID 32046105, 2020). "In this study, we explored the potential role of BECN1 in colorectal cancer (CRC) progression." (PMID 32358527, 2020). "Autophagy induced in colorectal cancer cells in response to starvation, the dual PI3K-MTOR inhibitor PI-103, the metabolic drug DCA, or the autophagy-inducing peptide Tat-Beclin 1, was associated with increased levels of ChoPLs and a reduction in PCho as measured by 1H-MRS." (PMID 31517566, 2020). "In gastric and colorectal cancer, the expression of BECN1 remained a high level in tumor tissues." (PMID 31272261, 2019). "Previous studies have shown that autophagy-related proteins are present in colorectal cancer as assessed by an LC3β protein expression level of 74 % to almost 100 % and by a beclin-1 protein expression level of 71–83 %, which is consistent with the findings of the present study." (PMID 26965179, 2016). "The prognostic significance of LC3β or beclin-1 for colorectal cancer is also contradictory." (PMID 26965179, 2016). "Hypermethylation of five autophagy-related genes, BECN-1, ATG16L2, ULK2, BNIP3 and a variant of LC3A, were previously reported respectively in BC, leukemia, astrocytoma, colorectal cancer and esophageal carcinoma and these data demonstrated that this hypermethylation was correlated to tumor grade." (PMID 26474850, 2015).
colorectal cancer (continued). "The deregulation of autophagy regulators has been observed in different types of cancers, such as the monoallelic deletion of Beclin-1 gene in human breast, ovarian and prostate cancers; the frameshift mutations of UVRAG and other ATG genes in gastric and colorectal cancers." (PMID 25026290, 2014). "For example, Beclin 1 expression is upregulated in gastric cancer, colorectal cancer, intrahepatic cholangiocellular carcinoma, and extranodal natural killer T-cell lymphoma, but is downregulated in high-grade gliomas, nasopharyngeal carcinoma, and esophageal squamous cell carcinoma." (PMID 24675697, 2014). "Survival analysis indicated that Beclin 1 expression was not linked to favorable prognosis of the patients with colorectal carcinoma (p > 0.05)." (PMID 25196438, 2014). "Beclin 1 has an important role in growth and metastasis of colorectal cancer." (PMID 20842118, 2010). "In addition, Hu’s team showed that the lower expression of BECN1 was associated with a poor prognosis in CRC, suggesting that BECN1 may act as a suppressor and represent a new prognostic marker for patients with colorectal cancer." (PMID 36830954, 2023). "Whether BECN1 can regulate the cell cycle progression of colorectal cancer cells remains unknown." (PMID 36230664, 2022). "Concerning the results of apoptosis, together with the impact of autophagy induction and inhibition on apoptosis, we hypothesized that EGCG could turn autophagy into apoptosis by promoting autophagy and Beclin‐1 cleavage, which increased the toxicity of irinotecan in colorectal cancer cells." (PMID 34132471, 2021). "The interaction induced PTBP1 cytoplasmic translocation and stabilized BECN1 mRNA in a PTBP1-dependent manner, thereby promoting colorectal cancer development." (PMID 40790019, 2025). "Clinical data further confirmed a significant correlation between the expression of ABHD5 and the expression of BECN1, LC3-II, and CASP3 in human colorectal cancer tissues." (PMID 39328203, 2024). "For example, in colorectal cancer cells, the suppression of key autophagy regulators, such as members of the ATG family or Beclin-1, have been shown to interfere with the repair of radiation-induced DNA damage." (PMID 35888608, 2022). "For example, SOX2 was shown to increase the expression of Beclin 1 and facilitate the maturation of autophagosomes, promoting the EMT and CSC properties of colorectal cancer." (PMID 36187468, 2022). "In colorectal cancer, IL-6 activates autophagy by the interaction of JAK2 and Becn1 because JAK2 acts as a protein kinase that phosphorylates Becn1 at Y333 to promote autophagy initiation." (PMID 36311768, 2022). "It has been reported that genetic inhibition of BECN1 or UVRAG potentiated IR-induced DNA double-strand breaks (DSBs) and cell death in colorectal cancer cells." (PMID 33718194, 2021). "Here the authors show that IL-6 activates autophagy in colorectal cancer through the interaction between JAK2 and autophagy regulator, BECN1, which leads to chemotherapeutic resistance." (PMID 34131122, 2021). "In the present study, we demonstrated that IL-6 activates autophagy in colorectal cancer, leading to the interaction between JAK2 and BECN1." (PMID 34131122, 2021). "Autophagy has been reported to be deregulated in CRC, and autophagy molecules such as Beclin 1, p62/sequestosome and LC3 are overexpressed in a high percentage of colorectal carcinomas." (PMID 33809172, 2021). "The aim of this study was to determine, via in silico methods, miRNA’s importance in BECN1, LAMP2, and PINK1 regulation and their possible role in the epigenetic changes in colorectal cancer." (PMID 33322704, 2020). "The study aimed to find those microRNAs (miRNAs) important in BECN1, LAMP2, and PINK1 regulation and to determine the possible role of the epigenetic changes in examined colorectal cancer using an in silico approach." (PMID 33322704, 2020).
colorectal cancer (continued). "The results from our study showed that novel compounds had ability to decrease the concentration of beclin-1, LC3A and LC3B in both analyzed colorectal cancer cell lines." (PMID 32717981, 2020). "Although dysregulation of the key autophagy proteins Beclin 1 and LC3 have been studied in a wide variety of tumors, the role of these proteins in colorectal cancer is ambiguous." (PMID 30374741, 2018). "In this study, we demonstrate for the first time that aspirin acetylated Beclin 1 in HCT116 and SW480 colorectal cancer cells." (PMID 29088823, 2017). "In colorectal cancer, high CHAC2 expression was also correlated with XBP-1s, active caspase-3 or Beclin 1 high expression with a correlation coefficient of 0.526 (P<0.001), 0.319 (P<0.001) and 0.433 (P<0.001), respectively." (PMID 28837156, 2017). "Here we investigated the potential prognostic value of the autophagy-related proteins Beclin-1, p62, LC3 and uncoordinated (UNC) 51-like kinase 1 (ULK1) in a cohort of colorectal cancer (CRC) specimens." (PMID 27444698, 2016). "Although dysregulation of Beclin 1 and LC3 have been investigated in a wide variety of tumors, the role of these proteins in colorectal carcinoma was still controversial, especially when the survival prognosis was involved." (PMID 25762626, 2015). "To gain insight into the mechanism(s) by which tumor cell autophagy can confer treatment resistance, we examined the ability of Beclin 1 and/or its cofactor UVRAG to regulate the DNA damage response and centrosome number in colorectal cancer (CRC) cell lines." (PMID 24956373, 2014). "We found that siRNA knockdown of Beclin 1 or UVRAG can increase radiation-induced DNA double strand breaks (DSBs), shown by pATM and γH2Ax, and promote colorectal cancer cell death." (PMID 24956373, 2014). "Differential transcriptional patterns of BECN1, PINK1, and LAMP2 were observed across colorectal cancer stages, suggesting that distinct autophagy pathways may be differentially regulated in inflammation-associated and sporadic colorectal tumorigenesis." (PMID 41614861, 2025). "The transcriptional activity of genes involved in the autophagy process (LAMP-2, BECN1, PINK1, FOXO1) in colorectal cancer biopsies in four clinical stages of adenocarcinoma (CSI, CSII, CSIII, CSIV) was compared with that of controls (colon samples assessed as histopathologically normal)." (PMID 36830954, 2023). "In this study, we show that the expression of nuclear Beclin 1 is upregulated in colorectal cancer with a negative correlation to RB protein expression." (PMID 36230664, 2022). "In colorectal cancer cells, EUG was identified as pro-autophagic compound, where the active fraction of clove (oleanonic acid and eugenol) increased LC3B I and II and Beclin-1 protein expression." (PMID 33509300, 2021). "In addition, our results indicate that BECN1 Y333 phosphorylation can be used as a predictive marker for poor prognosis in CRC and as a marker for the potential benefit of colorectal cancer chemotherapy and the early identification of chemotherapy resistance." (PMID 34131122, 2021). "It has been demonstrated that wogonin (4–16 μM) exerted its anticancer effects on human colorectal cancer cells (SW48) by inducing both autophagic and apoptotic processes, as shown by the formation of autophagosomes, the increase in Beclin 1 and LC3 II expression." (PMID 32927836, 2020). "A study of colorectal cancer, using an Abcam LC3B polyclonal antibody, found negative LC3B expression and absence of autophagy related proteins (Beclin 1 ATG5 LC3B) are associated with poor survival." (PMID 26265176, 2015). "In summary, we found that Beclin 1 and UVRAG regulate the DNA damage/repair response that may utilize NHEJ to repair DSBs in irradiated colorectal cancer cells." (PMID 24956373, 2014).
colorectal cancer (continued). "Here, we revealed that DSF activates autophagy in colorectal cancer (CRC) cells via dual mechanisms: compensatory autophagy induction through proteasome inhibition by targeting the p97-NPL4 axis, and transcriptional upregulation of the autophagy-related gene BECN1 via FOS gene activation." (PMID 41387670, 2025). "As a matter of fact, a high percentage of positive immunohistochemical staining of SPINK1 was observed in colorectal cancer patients, and interestingly, Chang Hyeok Ahnalso noticed that the increased expression of Beclin-1 was detected in 95% of the tumor tissues of the CRC patients." (PMID 37305325, 2022).
gastric cancer (103 papers, 2010 to 2025). A primary or metastatic malignant neoplasm involving the stomach. "GPE downregulates Beclin‐1, a critical protein for autophagy and autophagosome formation, which is often overexpressed in gastric cancers and linked to metastasis and poor prognosis." (PMID 40452796, 2025). "Analysis of the obtained results revealed that Les-4367 caused a reduction in Beclin-1 concentrations in the tested human gastric cancer cell line." (PMID 37047765, 2023). "For example, reduced Beclin-1, which regulates autophagy, has been associated with worse prognosis in gastric cancer by several studies." (PMID 33859932, 2021). "We retrieved fifteen articles about the relationship between Beclin 1 expression and cancer risk, clinicopathological or prognostic features of gastric cancer for meta-analysis." (PMID 33425768, 2020). "Becn1 overexpression was found to inhibit proliferation, glucose metabolism, migration and invasion of gastric cancer cells, whereas its knockdown caused the opposite effects." (PMID 33425768, 2020). "Here, we performed meta-analysis and found that down-regulated Beclin 1 expression in gastric cancer was positively linked to lymph node metastasis, TNM staging, dedifferentiation and poor prognosis, in agreement with our bioinformatics findings." (PMID 33425768, 2020). "There was significant association between Beclin 1 expression and favorable overall survival in patients with gastric cancer (OR=1.34, 95% CI: 1.15–1.56, P=0.0002)." (PMID 33425768, 2020). "Here, meta- or bioinformatics analysis showed that either Beclin 1 protein or mRNA expression was positively linked to the favorable prognosis of the patients with gastric cancer." (PMID 33425768, 2020). "Low expression of Beclin-1, a well-known marker of autophagy, associated with high Bcl-xL was shown to predict a malignant phenotype and poor prognosis of stomach cancer." (PMID 30742638, 2019). "The high expression of SIRT1 and Beclin-1 (Atg6) is associated with shorter overall survival and reduced relapse-free survival in gastric cancer patients." (PMID 31492861, 2019). "In line with the role of Beclin-1 in gastric cancer, but contrast to its role in papillary thyroid cancer, we found that the lower expression of Beclin-1 was significantly linked to less lymph node metastasis." (PMID 29545906, 2018). "Consistently, decreased Beclin 1 level, closely associated with upregulated Bcl-xL expression, predicts increased malignant phenotype and poor prognosis of gastric cancer." (PMID 26910278, 2016). "According to Lee's report, only 2.8% (5/180) of the gastric cancer samples harbor beclin 1 gene mutation." (PMID 26910278, 2016). "In line with previous research, our study showed that low expression of BECN1, an essential autophagy initiator, was associated with advanced clinical stage of gastric cancer patients." (PMID 26497999, 2015). "Immunoblotting revealed markedly induced autophagy in low grade differentiated gastric adenocarcinoma, indicated by elevation of microtubule-associated protein 1 light chain 3-I/II conversion and Beclin 1 in human gastric carcinomas." (PMID 24527069, 2014). "In addition, studies have further suggested that metformin promotes Beclin1-dependent autophagy to inhibit the progression of gastric cancer, which associated with changing the mRNA expression levels of LC3B and Beclin-1." (PMID 35463631, 2022). "In addition, the frameshift mutations of ultraviolet radiation resistance-associated gene (UVRAG), which binds to Beclin 1 and triggers autophagy activation, is also found in gastric cancers with high MSI (9.4%; 3/32)." (PMID 26910278, 2016). "In both colorectal and gastric cancers where BECN1 mutations rarely occur, decrease of BECN1 expression in cancer cells could be an inactivation mechanism of BECN1 tumor suppressor functions." (PMID 26802026, 2016).
gastric cancer (continued). "Furthermore, we found low beclin-1 expression was strongly associated with decreased survival in gastric cancer patients (P = 0.011) and the intravascular embolus subset (P = 0.017)." (PMID 23029344, 2012). "However, there are still relatively few studies that have investigated the association between Beclin 1 and gastric cancer." (PMID 23029344, 2012). "The use of Adenovirus vector to express XAF1 in gastric cancer cells promotes autophagy through increasing Beclin-1 levels and inhibiting the Akt/p70S6K pathway, leading to enhanced apoptosis simultaneously." (PMID 39650649, 2024). "The novelty of our study is highlighted from the CagA-mediated reduction of BECN1 expression and autophagic flux assay in human gastric cancer cells infected with Hp-WT and Hp-ΔcagA in the in vitro experiments." (PMID 37740192, 2023). "In cell lines derived from solid tumors (colon and gastric cancers), BECN1 ablation drastically decreases OXPHOS and lipid degradation and shifts cellular metabolism towards aerobic glycolysis, with increases in glucose uptake and lactate production." (PMID 37887330, 2023). "The obtained results showed that Les-4367 alone, as well as in combination with trastuzumab or pertuzumab, decreased Beclin-1 levels in the gastric cancer cell line." (PMID 37047765, 2023). "Beclin-1 expression in other tumors is lower than in normal tissues, but studies have shown that Beclin-1 is overexpressed in gastric cancer tissues." (PMID 35719323, 2022). "Downregulation of Beclin-1 is correlated to the incremental reprogramming in glucose metabolism, cell invasion and proliferation in gastric cancer." (PMID 35884904, 2022). "Beclin-1 overexpression was found to markedly attenuate the ability of gastric cancer cells to migrate and invade possibly due to VEGF hypoexpression." (PMID 35463631, 2022). "The results of our study showed that the oncogenic ability of cell proliferation and cancer promotion, represented by SKP2 expression in gastric cancer tissues, was repressed by the expression of Beclin-1 and FOXP3 and thus responded to the survival outcome." (PMID 34414959, 2021). "Either Beclin 1 mRNA or protein hyperexpression was seen in colorectal and gastric cancers in comparison to precancerous lesion or mucosa." (PMID 33425768, 2020). "Reportedly, Beclin 1 overexpression augmented the apoptotic induction of cis-diamminedichloroplatinum via enhancing Caspase-9 activity in gastric cancer cells." (PMID 33425768, 2020). "Bioinformatics analysis showed higher Becn1 mRNA expression in intestinal- than diffuse-type carcinomas (P<0.05), and in male than female gastric cancer patients (P<0.05)." (PMID 33425768, 2020). "According to TCGA databases, Becn1 mRNA expression was found to be lower in gastric cancer than normal mucosa (P<0.05)." (PMID 33425768, 2020). "We collected 986 cancers and 786 controls and found down-regulated Beclin 1 expression in gastric cancer (P=0.02)." (PMID 33425768, 2020). "Here, the aggressive phenotypes and relevant proteins were examined after Beclin 1 expression was altered in gastric cancer cells." (PMID 33425768, 2020). "Here, we analyzed the effects of Beclin 1 expression on the aggressive behaviors and phenotypes of gastric cancer cells, and clarified relevant mechanisms." (PMID 33425768, 2020). "Flow cytometry showed G1 or S arrest, and apoptotic induction in Becn1 transfectants of gastric cancer cells (P<0.05)." (PMID 33425768, 2020). "Meta-analysis showed that down-regulated Beclin 1 expression in gastric cancer was positively with lymph node metastasis, TNM staging, dedifferentiation and poor prognosis (P<0.05)." (PMID 33425768, 2020). "After transfected with Becn1-expressing plasmid, the appearance of gastric cancer cells became irregular, vacuolar, polynucleate and protrudent." (PMID 33425768, 2020).